FCGR1BP (Fc gamma receptor Ib, pseudogene )
Synonyms: CD64b; FCG1; FCGR1; FCGR1B; FcRI; FcgammaRIa; IGFR1; IGFRB
Gene: Long non-coding RNA gene on chromosome 1 (121,042,602 to 121,103,109, forward strand). Ensembl gene ENSG00000291135.
Diseases named in the same sentence as FCGR1BP in open-access papers:
FCGR1BP is named in the same sentence as 1 disease in open-access papers, as found by Europe PMC text mining. Sharing a sentence is not in itself a finding about the gene and the disease.
FCGR1BP shares sentences with these, for which no sentence is quoted: viral infections (1 paper).